ZMYND19 (zinc finger MYND-type containing 19)
Description:
May be involved as a regulatory molecule in GPR24/MCH-R1 signaling.
Synonyms: MIZIP
Tractability: Antibody: UniProt places it where antibodies can reach, with high confidence; its Gene Ontology location is reachable by antibodies, with medium confidence. PROTAC: ubiquitination databases record sites on it.
Gene: Protein-coding gene on chromosome 9 (137,582,081 to 137,590,512, reverse strand). Ensembl gene ENSG00000165724.
Subcellular location: Cytoplasm; Cell membrane
Subcellular location (Human Protein Atlas): Golgi apparatus; Vesicles
Gene Ontology:
Molecular function: protein binding
Cellular component: cytoplasm; membrane; synapse; plasma membrane
Genetic constraint (gnomAD): Loss-of-function variants: 17 observed, 30.88 expected, observed/expected ratio (o/e) 0.55, 90% interval 0.38 to 0.83. The upper end of that interval is the gene's LOEUF score, 0.83, which puts it in group 3 of 6, group 1 being the genes least tolerant of losing a copy. Missense variants: 250 observed, 293.38 expected, observed/expected ratio (o/e) 0.85, 90% interval 0.77 to 0.95. Synonymous variants: 124 observed, 112.37 expected, observed/expected ratio (o/e) 1.1, 90% interval 0.95 to 1.28.
Homologues: Orthologues: chimpanzee ZMYND19 (100% identical), macaque ZMYND19 (100% identical), mouse Zmynd19 (100% identical), rat Zmynd19 (100% identical), guinea pig ZMYND19 (99% identical), dog ZMYND19 (98% identical), pig ZMYND19 (91% identical), zebrafish zmynd19 (81% identical), rabbit ZMYND19 (78% identical), tropical clawed frog zmynd19 (61% identical), Drosophila melanogaster Zmynd10 (15% identical). Paralogues in human: ZMYND10 (21% identical), MSS51 (13% identical).